GSK3B (glycogen synthase kinase 3 beta)
Diseases named in the same sentence as GSK3B in open-access papers (continued):
Sharing a sentence is not in itself a finding about the gene and the disease.
leukoplakia (2 papers, 2022 to 2025). A white patch or plaque on a mucous membrane that cannot be characterized clinically or pathologically as any other disease. "Similar to how the FTH1P3 lncRNA modulates PI3K/Akt/GSK3β/Wnt/β-catenin signaling to promote oncogenesis, LOLA1 (lncRNA oral leukoplakia progressed associated 1) can influence AKT/GSK‐3β signaling to assist the EMT induction." (PMID 36106022, 2022). "Using a GEO database of oral carcinogenesis (GSE85195), the transcriptional modification of 19 Wnt ligands and 4 key regulatory proteins of β-catenin, including E-cadherin, APC, AXIN and GSK3B, during leukoplakia, and early and late stages OSCC, was determined." (PMID 40421179, 2025). "Additionally, transcriptional levels of GSK3B and AXIN are significantly higher than normal oral mucosa during leukoplakia, and early and late stage OSCC." (PMID 40421179, 2025).
lipid metabolism disorder (2 papers, 2022 to 2025). "We selected oxidative stress and apoptosis-related proteins Fas and cytochrome C, inflammation-related proteins P65 and JNK1/2, lipid metabolism disorder-related proteins SREBP1 and leptin, and insulin resistance-related proteins GSK3β and CYP2E1 for subsequent experimental validation." (PMID 35845577, 2022).
lupus nephritis (2 papers, 2012 to 2025). Glomerulonephritis in the context of systemic lupus erythematosus. "Moreover, glomerular expression of GSK3β was elevated by 2.6-fold in FSGS and 3.1-fold in lupus nephritis in human kidney biopsies based on computerized morphometric analysis." (PMID 40526103, 2025).
Marfan syndrome (2 papers, 2023 to 2024). A disorder of the connective tissue. "Finally, high-throughput screening was demonstrated in an activity-based system that screened 1,022 small-molecule inhibitors in a genetically engineered model for Marfan syndrome (MFS), revealing glycogen synthase kinase 3 beta (GSK3β) as a positive hit among other interesting targets." (PMID 38359791, 2024).
metastatic cancers (2 papers, 2015). A carcinoma which has spread from the original site of growth to another anatomic site. "Genes in the CMCG group (CDK4, CDK6, CDK8, GSK3B) had the most frequent copy number alterations in 86% of the primary and 65% of the metastatic cancers." (PMID 26420498, 2015). "We also observed very high overexpression of GSK3β in the tongue tissue samples of normal, benign, malignant and even metastatic cancers." (PMID 25645517, 2015).
metastatic melanoma (2 papers, 2014 to 2025). A melanoma that has spread from its primary site to another anatomic site. "To further investigate the molecular mechanism underlying the effects of ArcA in metastatic melanoma, we examined its impact on glycogen synthase kinase-3β (GSK-3β), a protein crucial for cell proliferation and metastasis." (PMID 39948552, 2025). "Further investigation is needed to gain detailed insights into the mechanisms underlying ArcA-mediated GSK-3β activity and its tumor suppressive effects in metastatic melanoma." (PMID 39948552, 2025). "Thus, the ArcA-induced dephosphorylation (Ser9) of GSK-3β may enhance the cell cycle inhibitory effects, thereby enhancing its cytotoxic effects against metastatic melanoma." (PMID 39948552, 2025). "Moreover, ArcA significantly inhibited cell migration and invasion in metastatic melanoma cell lines, accompanied by reduced expression levels of p-GSK-3β (Ser9), MMP-9, and MMP-13, suggesting that its anti-metastatic effects may be partially mediated through GSK-3β, MMP-9, and MMP-13." (PMID 39948552, 2025).
migraine (2 papers, 2020 to 2025). "In addition, GSK3B activation may be associated with increased neuroinflammation and pain sensitivity during migraine attacks." (PMID 41155719, 2025). "In addition, GSK3B inhibitors and Sestrin1 activators may be investigated to control migraine-associated inflammation and neurovascular dysfunction." (PMID 41155719, 2025). "The increase in GSK3B and the decrease in Sestrin1 indicate that neuroinflammation and cellular stress are important mechanisms contributing to migraine pathophysiology." (PMID 41155719, 2025). "In our study, a significant increase in GSK3B levels was observed in migraine patients." (PMID 41155719, 2025). "In addition, increased GSK3B and decreased Sestrin1 levels indicate that neuroinflammation and cellular stress make significant contributions in individuals with migraine." (PMID 41155719, 2025). "Together, these findings argue that NO could stimulate TGNs to release of CGRP as well as other migraine-related factors, likely by activating GSK-3β, providing a novel mechanism underlying a potential feed-forward loop between NO and CGRP in migraine." (PMID 32276265, 2020). "Therefore, these in vitro findings warrant further validation in vivo in animal models, as well as clinical investigation in patients with migraine, by taking advantage of the availability of various GSK-3β inhibitors currently ongoing clinical trials." (PMID 32276265, 2020). "Inhibition of GSK-3β has been shown to alleviate neuroinflammation and pain, raising a possibility that GSK-3β may also be involved in migraine." (PMID 32276265, 2020). "Furthermore, GSK-3β inhibition resulted in a marked reduction in expression of CGRP as well as other migraine-related factors, including substance P, cholecystokinin, and prostaglandin E2." (PMID 32276265, 2020). "Together, our observations suggest that GSK-3β may represent a novel target for the treatment of migraine." (PMID 32276265, 2020). "Therefore, our findings strongly support a notion that GSK-3β may represent a novel target for the prevention and treatment of migraine." (PMID 32276265, 2020). "The mechanism underlying this event involves GSK-3β activation in TGNs, likely in association with the inactivation of the PI3K/Akt pathway, while inhibition of GSK-3β effectively blocked SNAP-induced expression and production of CGRP and other migraine-related factors (e.g., SP, CCK, and PEG2)." (PMID 32276265, 2020). "The GSK3B, Keap1, oxLDL, TOS, and OSI levels were significantly higher in migraine patients compared with the control group (p < 0.001)." (PMID 41155719, 2025). "Our study findings revealed that Keap1, oxidized LDL (oxLDL), Glycogen Synthase Kinase-3 Beta (GSK3B), total oxidant level (TOS), and oxidative stress index (OSI) levels were significantly higher in migraine patients compared to controls." (PMID 41155719, 2025). "However, the functional role of GSK-3β in migraine remains virtually unknown." (PMID 32276265, 2020). "Furthermore, GSK-3β might act to mediate NO-induced activation of TGNs at least in part, via the activation of NF-κB, raising a possible link between neuroinflammation and peripheral or central sensitization during migraine." (PMID 32276265, 2020). "In this study, we found that inhibition of GSK-3β (e.g., by AR-A014418) largely diminished SANP-induced expression and production of CGRP, as well as other known migraine-related factors (e.g., SP, CCK, PEG2) in cultured cells." (PMID 32276265, 2020). "In addition, increased levels of oxidized LDL (oxLDL) and glycogen synthase kinase-3 beta (GSK3B), which are oxidative stress markers, confirmed that the oxidative stress burden was high in migraine patients." (PMID 41155719, 2025). "Together, these results argue that activation of GSK-3β might functionally contribute to NO-induced expression and production of CGRP as well as other migraine-related factors (e.g., SP, CCK and PEG2) in TGNs." (PMID 32276265, 2020).
migraine (continued). "In addition, this study found that the plasma Keap1, oxLDL, Nrf2, GSK3B, Sestrin, TOS (total oxidant level), TAS (total antioxidant level) levels, and OSI (oxidative stress index) values of migraine patients were statistically significantly different compared with the control group." (PMID 41155719, 2025). "Therefore, we identified the GSK-3β signaling pathway as a novel mediator for NO to induce the expression and release of CGRP in TGNs and thus may serve as a potential target for the treatment of migraine." (PMID 32276265, 2020).
myotonic dystrophy (2 papers, 2021 to 2023). An inherited progressive disorder affecting the muscles. "Currently, one GSK3β inhibitor, Tideglusib, has successfully gone through phase II trials for myotonic dystrophy." (PMID 36669494, 2023).
Neurofibrillary tangles (2 papers, 2023 to 2025). Pathological protein aggregates formed by hyperphosphorylation of a microtubule-associated protein known as tau, causing it to aggregate in an insoluble form. "REST directly targets and represses genes that mediate phospho-tau accumulation in 3xTg mice, including the tau kinases GSK3β and CDK5 which have been implicated in neurofibrillary tangle formation." (PMID 37919281, 2023). "Notably, one of the kinases that phosphorylates β-catenin towards degradation is GSK3β, which is well known for promoting tau hyperphosphorylation and thus neurofibrillary tangle formation in AD." (PMID 40221411, 2025).
oral mucositis (2 papers, 2016 to 2019). Inflammation of the mucous membranes of any of the structures in the mouth. "Moreover, GSK3β rs375557 and adenomatous polyposis coli gene (APC) rs454886 polymorphisms were correlated with acute grade 3–4 radiation-induced dermatitis and oral mucositis, respectively." (PMID 27769064, 2016). "In conclusion, we found that CTNNB1 rs1880481, CTNNB1 rs3864004, and GSK3B rs375557 were correlative with the curative efficacy of RT, and that GSK3β rs375557 and APC rs454886 were correlative with acute grade 3–4 radiation-induced dermatitis and oral mucositis." (PMID 27769064, 2016).
Osteopenia (2 papers, 2021 to 2023). Osteopenia is a term to define bone density that is not normal but also not as low as osteoporosis. "According to the newest reports, BHLHE40 deficiency resulted in accelerated osteopenia through attenuated PI3KCA/Akt/GSK3β signaling." (PMID 34917665, 2021).
ovarian adenocarcinoma (2 papers, 2003 to 2021). An adenocarcinoma that arises from the ovary. "Mutations of the β-catenin gene at the binding site for GSK3β was demonstrated in 16–30% of the endometrioid type of ovarian adenocarcinomas, but not in other types of ovarian tumours." (PMID 14520463, 2003).
papillary thyroid cancer (2 papers, 2019 to 2022). "miR-215 was found to suppress papillary thyroid cancer metastasis by regulating the EMT via the AKT/GSK-3β/Snail signaling." (PMID 35847962, 2022).
parathyroid tumors (2 papers, 2012 to 2021). "As menin is a known primary affected tumour suppressor in parathyroid tumours, it is possible that its dysfunction would cause a disinhibition of GSK3β mediated degradation of PRLr, hence stabilizing the long/ΔS1 isoforms." (PMID 22606260, 2012). "35/37 parathyroid tumours and fallopian tube expressed total GSK3β at comparable levels, while in 2 tumours only weak expression was observed." (PMID 22606260, 2012). "Additionally, patients treated with lithium, which most likely leads to GSK3β phosphorylation, are known to be highly prone to parathyroid tumours." (PMID 22606260, 2012).
peripheral nerve injury (2 papers, 2015 to 2020). Injury to a peripheral nerve. "So, this study attempted to evaluate the role of GSK-3β in apoptosis following peripheral nerve injury." (PMID 32483472, 2020). "In conclusion, this study finding suggested that reducing the p-GSK-3β/t-GSK-3β ratio could be considered as a helpful strategy for reducing apoptotic cells and subsequent neuropathic pain during peripheral nerve injury." (PMID 32483472, 2020). "The study findings suggested that increasing the p-GSK-3β/t-GSK-3β ratio might be a helpful strategy for reducing the apoptotic cells and subsequent neuropathic pain during peripheral nerve injury." (PMID 32483472, 2020). "Thus, this study aimed to evaluate the contribution of p-GSK-3β/t-GSK-3β ratio in spinal dorsal horn apoptosis following peripheral nerve injury." (PMID 32483472, 2020).
Peritoneal Fibrosis (2 papers, 2018 to 2022). Disorder characterized by a wide range of structural changes in PERITONEUM, resulting from fibrogenic or inflammatory processes. "In contrast, the PDF-triggered GSK3β hyperactivity was averted after Sal A, concomitant with the protective effect on peritoneal fibrosis." (PMID 35321474, 2022). "As such, therapeutic targeting of GSK3β is likely a promising strategy to treat peritoneal fibrosis." (PMID 35321474, 2022). "In addition, the protective effect of Sal A on peritoneal fibrosis was recapitulated in vitro in peritoneal mesothelial cells injured with hypertonic dextrose and abolished by overexpression of the constitutively active GSK3β." (PMID 35321474, 2022). "In conclusion, Tamoxifen significantly attenuated HG dialysate-induced peritoneal fibrosis via inhibition of EMT progression in peritoneum, at least in part through inhibition of GSK-3β/β-catenin axis activation." (PMID 30061174, 2018).
peroxisomal disease (2 papers, 2018 to 2022). A group of congenital disorders of lipid metabolism, caused by loss of the normal peroxisomes. "Exacerbated GSK‐3β activity is also present in other peroxisomal diseases, like rhizomelic chondrodysplasia punctata, in which plasmalogen deficiency leads to AKT inactivation and GSK‐3β activation." (PMID 29997171, 2018). "Future work should address and quantify both the functionality of the NRF2 pathway in rhizomelic chondrodysplasia punctata and the AKT/GSK‐3β/NRF2 axis in other peroxisomal disorders, given the possibility of targeted treatments like DMF, for these metabolic diseases." (PMID 29997171, 2018).
pharyngeal cancer (2 papers, 2023 to 2026). "Activation of the Akt/GSK-3β/cyclin D1 pathway, leading to the proliferation of pharyngeal cancer cells." (PMID 36908412, 2023).
polyposis (2 papers, 2023 to 2025). "This prevents GSK3β from phosphorylating microtubule-associated proteins such as adenomatous polyposis coli: when adenomatous polyposis coli is phosphorylated by GSK3β, it displays poor binding to microtubules, which reduces microtubule stability, as shown by their decreased acetylation." (PMID 40164682, 2025). "Stable expression of cytoplasmic β-catenin depends on a poly-complex that includes glycogen synthase kinase 3β (GSK-3β), axin, casein kinase Iα, and adenomatous polyposis coli 24,25." (PMID 36741266, 2023).
postmenopausal osteoporosis (2 papers, 2021 to 2026). Metabolic disorder associated with fractures of the femoral neck, vertebrae, and distal forearm. "In Group 3 (postmenopausal osteoporosis, without fractures), the REL of: GSK3B and SFRP1 positively correlated with TH BMD (R=0.560, p = 0.046 and R=0.703, p = 0.007) and TH T-score (R=0.560, p = 0.046 and R=0.703, p = 0.007), respectively." (PMID 33357212, 2021).
proteinopathies (2 papers, 2020 to 2021). "Under some pathological conditions, GSK-3β activity is upregulated, exerting its adverse influence on cholinergic signaling increasingly and, at the same time, inducing phosphorylation events critical to the development of proteinopathies." (PMID 32392535, 2020). "Given that Tideglusib have shown good safety and tolerability in patients suffering from different neurological diseases, it is proposed that the repositioning of this in-house designed GSK-3β inhibitor could be a valid therapeutic strategy for the treatment of ALS and other TDP-43 proteinopathies." (PMID 34445680, 2021).
pulpitis (2 papers, 2017 to 2023). Inflammation of the dental pulp. "Our findings provide direct evidence that SDF-1/CXCR4 axis induces hDPSCs migration through FAK/PI3K/Akt and GSK3β/β-catenin pathways, implicating a novel mechanism of dental pulp repair and a possible application of SDF-1 for the treatment of pulpitis." (PMID 28067275, 2017).
rectal adenocarcinoma (2 papers, 2023 to 2025). "In a further analysis, we determined the alteration frequencies of c-Met/GSK3β/MYC/CCND1 gene signatures in CRC, COAD, and rectal adenocarcinoma (READ) tissues." (PMID 36672275, 2023).
retinal degeneration (2 papers, 2018 to 2022). Degeneration of the retina. "Regarding cell survival, only one functional allele of Gsk3β leads to reduced cell death in mouse models of retinal degeneration, similar to drug-induced GSK3 inhibition, offering a powerful genetic model to identify specific deregulated target genes (our unpublished data)." (PMID 36139472, 2022). "Although reducing GSK3 activity appears beneficial for neuroprotection in models of retinal degeneration, the complete deletion of Gsk3α and Gsk3β, specifically in retinal progenitors, leads to massive cell death by apoptosis." (PMID 36139472, 2022). "Compared with wild-type controls, GSK-3β expression (mRNA and protein) remained unchanged during the retinal degeneration period." (PMID 29661219, 2018). "It was shown that NF-κB is activated in rd mice and light-induced retinal degeneration Interestingly, GSK3β was shown to facilitate NF-κB transactivation by TNF-α since GSK3β deficient mouse embryonic fibroblasts exhibit defective NF-κB activation in response to TNFα." (PMID 36139472, 2022).
Rett syndrome (2 papers, 2020 to 2022). A severe neurodevelopmental disorder affecting the central nervous system. "Another study reinforces Gsk3β-mediated neuroinflammation, partially by enhancing nuclear factor kappa b subunit 1 (Nfkb1) signaling, where the inhibition of Gsk3β with the SB216763 inhibitor reduces Nfkb1 signaling and inflammation levels, in a mouse model of Rett syndrome." (PMID 35203447, 2022).
Salmonella Infections (2 papers, 2014 to 2017). Infections with bacteria of the genus SALMONELLA. "We have identified how GSK-3β regulates the pro-inflammatory reactions of heterophils in response to a Salmonella infection and characterized the molecular interactions central to this response." (PMID 26664916, 2014). "The phosphorylation of GSK-3β and β-catenin in regulating inflammatory cascade is not only unique to Salmonella infection however there are also reports regarding other Type three secretory system (TTSS) dependent pathogens involved in similar mechanism." (PMID 28430783, 2017).
serous ovarian cancer (2 papers, 2016 to 2021). "Our study show that knockdown of Wip1 facilitates an epithelial-mesenchymal transition through the activation of the Akt/GSK-3β signaling, leading to the enhanced invasion, migration and metastasis of serous ovarian cancer cells, while overexpression of Wip1 entirely reverses these effects." (PMID 27121065, 2016).
spinocerebellar ataxia type 1 (2 papers, 2017 to 2023). Spinocerebellar ataxia type 1 (SCA1) is a subtype of type I autosomal dominant cerebellar ataxia (ADCA type I) characterized by dysarthria, writing difficulties, limb ataxia, and commonly nystagmus and saccadic abnormalities. "Moreover, ATXN1 regulates the cerebellar bioenergetics proteome through the GSK3b-mTOR pathway, which is altered in spinocerebellar ataxia type 1 (SCA1), an autosomal dominant neurodegenerative disorder." (PMID 29212253, 2017).
synucleinopathies (2 papers, 2014 to 2020). "GSK-3β inhibitors may be used as a potential therapeutic strategy to counteract the effects of ASN toxicity in synucleinopathies." (PMID 24722055, 2014).
systemic sclerosis (2 papers, 2021 to 2022). A chronic disorder, possibly autoimmune, marked by excessive production of collagen which results in hardening and thickening of body tissues. "Clinical research showed treatment with the specific inhibitor AR-A14418 aggravates the fibrotic phenotype of systemic sclerosis fibroblasts via inhibition of GSK-3β." (PMID 36684601, 2022). "By intervening in the hedgehog signaling pathway and the GSK‐3β signaling pathway, pirfenidone has shown an anti-fibrotic effect in interstitial lung disease secondary to systemic sclerosis." (PMID 33564498, 2021).
T-cell lymphomas (2 papers, 2022 to 2023). "In the T-cell lymphomas in our model, there is an increase in Total GSK-3β and a decrease in its inactive phosphorylated form." (PMID 37160922, 2023).